BRCA1 (BRCA1 DNA repair associated)
Diseases named in the same sentence as BRCA1 in open-access papers (continued):
Sharing a sentence is not in itself a finding about the gene and the disease.
ovarian carcinoma (continued). "We found that TLK loss induces resistance to PARPi in TNBC and ovarian cancer cells harboring BRCA1 mutations or deficiencies." (PMID 39844055, 2025). "Recent Danish papers on the distribution of gene variants in a 2006–08 cohort of patients with a suspected hereditary predisposition to breast and/or ovarian cancer found that 28% of the highly selected cohort had a pathogenic BRCA1 or BRCA2 variant." (PMID 40507299, 2025). "The integration of BRCA1/2 mutation testing into female breast and ovarian cancer screening has been extensively researched and deemed cost-effective, predominantly based on data from developed countries like the US and UK." (PMID 40567951, 2025). "Therapeutic synergy emerges from combined GPX4 inhibitor and PARP inhibitor treatment, which cooperatively induce ferroptosis in BRCA1-deficient ovarian cancer cells and potently inhibit tumor growth." (PMID 40342999, 2025). "We compared the transcriptomic profiles of breast and ovarian cancers harboring mutations in BRCA1 and BRCA2 to identify differential transcriptomic patterns of expression." (PMID 40647506, 2025). "PARP inhibitors have already been successfully used in BRCA1-deficient tumors such as pancreatic, prostate, breast and ovarian carcinomas." (PMID 40519304, 2025). "In ovarian cancer, pathogenic variants in BRCA1, BRCA2, RAD51C, RAD51D, and PALB2 predict PARP inhibitor efficacy, but this has not been established for other HRR-related genes." (PMID 40069561, 2025). "This article explores the importance of genetic mutations, such as BRCA1/2 mutations, in ovarian cancer and highlights recent advances in therapeutic strategies based on tumor molecular signatures." (PMID 40718421, 2025). "Germline and somatic mutations affecting HRR genes are relatively commonplace, affecting approximately one-third of ovarian carcinoma patients, with BRCA1 and BRCA2 mutations being the most prevalent." (PMID 40166687, 2025). "Identification of somatic and germline BRCA1/2 pathogenic variants in epithelial ovarian cancer (EOC) patients is essential for determining poly-(ADP-ribose)-polymerase (PARP) inhibitor sensitivity and genetic predisposition." (PMID 40323485, 2025). "A family history of breast or ovarian cancer is an important risk factor for ovarian cancer, with known genetic predispositions (primarily germline mutations in BRCA1 or BRCA2) accounting for 10%–15% of cases." (PMID 41169433, 2025). "Talazoparib was evaluated in phase I trials in patients with one of the following cancers: triple-negative breast cancer, ovarian cancer, prostate cancer, pancreatic cancer, and identified germline mutations of BRCA1 and BRCA2." (PMID 41155399, 2025). "Genetic screening of mainly patients with breast and ovarian cancer has identified numerous BRCA1/BRCA2 variants of uncertain significance (VUS) that remain unclassified owing to a lack of pedigrees and functional data." (PMID 40232841, 2025). "A case–control study further confirmed this finding in Asian, revealing that approximately 15.8% of ovarian cancer patients harbored mutations in the BRCA1 or BRCA2 genes in Pakistani countries." (PMID 40558241, 2025). "The risk of developing ovarian cancer for BRCA1 mutation carriers is about 44%, and for BRCA2 mutation carriers, it is about 17%." (PMID 40429755, 2025). "The risk of ovarian cancer in BRCA1/2 pathogenic variant carriers can be significantly reduced by risk-reducing salpingo-oophorectomy (RRSO), with a reported hazard ratio (HR) of 0.06, compared with that in non-carriers who did not undergo the procedure." (PMID 40862027, 2025). "Risk-reducing salpingo-oophorectomy (RRSO) can substantially reduce ovarian cancer incidence in women carrying pathogenic BRCA1 or BRCA2 variants, which cause hereditary breast and ovarian cancer syndrome." (PMID 40862027, 2025).
ovarian carcinoma (continued). "The tumor suppressor genes BRCA1/2 play a critical role in maintaining genetic stability by repairing DNA, and mutations in these genes can significantly increase the likelihood of ovarian cancer." (PMID 40896438, 2025). "A recent preclinical study with an AXL-targeted ADC conjugated to a pyrrolobenzodiazepine cytotoxin showed potentially promising results in a BRCA1-mutated ovarian cancer model, highlighting the potential benefit of ADCs with varied mechanisms of action." (PMID 41166388, 2025). "BRCA1/2 mutation carriers have a greater risk for developing breast and ovarian cancer, as part of the Hereditary Breast-Ovarian Cancer (HBOC) syndrome." (PMID 40422510, 2025). "This dual role of STING presents both challenges and opportunities for therapeutic strategies targeting BRCA1-deficient ovarian cancers." (PMID 39949780, 2025). "The National Comprehensive Cancer Network (NCCN) guidelines recommend RRSO for ovarian cancer risk reduction by age 35-40 years for BRCA1 mutation carriers, and by age 40-45 years for BRCA2 variant carriers." (PMID 40862027, 2025). "Restoration of DNA repair has been linked to resistance, as shown by the capability of secondary BRCA1 mutations to restore the wild-type gene reading frame in ovarian carcinomas with primary or acquired cisplatin resistance." (PMID 40083690, 2025). "For hereditary breast and ovarian cancer, multiple pathogenic mutations in the N-terminal domain of BRCA1 have been reported in patients." (PMID 40661454, 2025). "PARP inhibition in BRCA1-deficient ovarian cancer exploits synthetic lethality by targeting tumor cells’ reliance on PARP-mediated DNA repair and activates an immune response via the STING pathway." (PMID 39949780, 2025). "Secondly, while BRCA1 mutations predispose both to breast and ovarian carcinomas, BCs are significantly more frequent; therefore, we focused only on this category of cancer patients." (PMID 41374957, 2025). "PARP inhibitors have been used with great clinical success in ovarian cancer associated with mutations in the BRCA1 and BRCA2 genes." (PMID 41375669, 2025). "The eventual progression of BRCA1/2-mutated breast or ovarian cancer, even after treatment with PARP inhibitors, has limited the success of this therapy in the clinic, emphasizing the need to identify mechanisms of this acquired resistance." (PMID 40274769, 2025). "Studies have shown that mutations occurring beyond exon 11 of BRCA1 are associated with a 20% lower risk of ovarian cancer than mutations within exons 1–11." (PMID 40427158, 2025). "Subsequent studies sought to further analyze the resectability of BRCA1/2-mutated ovarian cancers, this time focusing on the rate of complete macroscopic resection." (PMID 40868967, 2025). "Simultaneously, the updated ACMG guideline highlights that PALB2 variants confer breast and ovarian cancer risks comparable to BRCA1/2 and recommends reporting these variants as secondary findings in clinical exome and genome sequencing." (PMID 40822464, 2025). "For example, hypermethylation of the Breast Cancer 1 (BRCA1) gene in ovarian cancer cells is associated with increased sensitivity to platinum-based chemotherapy." (PMID 39757310, 2025). "Poly (ADP-ribose) polymerase inhibitors (PARPi) demonstrate effective treatment outcomes in ovarian cancer patients with BRCA1/2 mutations or homologous recombination (HR) repair deficiencies, leveraging the principle of synthetic lethality." (PMID 42017177, 2025). "It is known that mutations in the BRCA1 gene are responsible for an increased risk of developing ovarian cancer." (PMID 40429755, 2025). "Several studies in the literature have demonstrated the potential chemo-preventive effect of oral contraceptives in reducing ovarian cancer risk among BRCA1 and BRCA2 mutation carriers." (PMID 41463165, 2025).
ovarian carcinoma (continued). "Secondary BRCA1 mutations able to restore the wild-type gene reading frame and DNA repair in ovarian carcinomas have been associated to resistance to cisplatin and PARP inhibitors 10, implying the need for new target discovery." (PMID 40083690, 2025). "BRCA1/2 pathogenic mutation causes not only breast or ovarian cancer but also prostate or pancreatic cancer." (PMID 39996890, 2025). "Mutations in BRCA1 are highly associated with familial breast and ovarian cancer and are also the likely driver of a variety of sporadic cancers." (PMID 40406258, 2025). "PARP Inhibitors were approved as first-generation synthetic lethal agents for advanced ovarian cancer with BRCA1 or BRCA2 mutations." (PMID 39885134, 2025). "This study suggests that ovarian carcinomas demonstrate better NACT outcomes in BRCA2- vs. BRCA1-mutated hereditary ovarian carcinomas, probably due to the higher sensitivity of the former to carboplatin-paclitaxel." (PMID 40547808, 2025). "Niraparib, approved for BRCA1/2-mutated ovarian cancer, and Rucaparib, approved for ovarian and prostate cancers, are also under evaluation for the treatment of PDAC in patients with known DNA repair mutations." (PMID 41009605, 2025). "In the case of hereditary ovarian cancers, they are associated with the carrier of mutations in the terminal BRCA1/BRCA2 genes." (PMID 40429755, 2025). "In the first stage, a patient with ovarian cancer is tested for the presence of BRCA1/2 pathogenic or likely-pathogenic variants using Next Generation Sequencing (NGS) from cancer tissue." (PMID 40002896, 2025). "The Chinese healthcare system is now actively promoting genetic testing for BRCA1/2 mutations among women with a family history of ovarian cancer." (PMID 40896438, 2025). "Women with germline mutations in the tumor suppressor gene breast cancer 1 (BRCA1) have a greatly increased lifetime incidence of breast and ovarian cancer." (PMID 41347767, 2025). "BRCA1 is a well-known tumor suppressor targeted by systemic therapy in multiple cancer types and is often mutated in familial breast and ovarian cancers." (PMID 41243969, 2025). "Conclusively, we demonstrate that methylstat increases susceptibility to olaparib-induced DSBs in PARPi-resistant ovarian cancer cells with a BRCA1-proficient background." (PMID 39915607, 2025). "Risk factors contributing to the development of ovarian cancer include a higher number of lifetime ovulatory cycles and genetic mutations such as BRCA1/2." (PMID 40507303, 2025). "Since then, additional recurrent mutations have been detected in the Polish population, and now a panel of 10–12 BRCA1/2 variants is commonly used as an initial screening tool for breast and ovarian cancer risk assessments in the population." (PMID 40002208, 2025). "Ovarian cancer mortality is reduced by up to 96% if a risk-reducing salpingo-oophorectomy [RRSO] is performed before ovarian incidence rises [age 35–40 years for BRCA1 carriers and age 40–45 years for BRCA2 GPV carriers]." (PMID 40427184, 2025). "Constitutional mosaic epimutations in BRCA1 have been linked to increased risk of breast and/or ovarian cancer." (PMID 41194282, 2025). "The most critical genetically determined risk factors for ovarian cancer (OvCa) are germline BRCA1 and BRCA2 mutations, which result in dysfunction of DNA repair mechanisms." (PMID 41008855, 2025). "Women who are heterozygous carriers of pathogenic BRCA1 alterations have significantly increased lifetime risks of developing breast and ovarian cancer and both male and female heterozygous carriers are at increased risk for pancreatic cancer." (PMID 40519302, 2025). "In Japan, the experience in genetic medicine that has been cultivated for hereditary breast and ovarian cancer treatment should be applied and utilized for patients with genetic variants other than BRCA1/2." (PMID 39831988, 2025).
ovarian carcinoma (continued). "For tubal/ovarian cancer, the average cumulative risk by the age of 80 is 44% [95%CI = 36–53] for BRCA1 and 17% [95%CI = 11–25] for BRCA2 GPV carriers, compared to a lifetime risk of 1.2% in the general population." (PMID 40427184, 2025). "This event likely links with the HRD onsetting LOH of chr17q in tumors with BRCA1 deficiency, which is more prevalent in dHpC tumor types such as breast and ovarian cancers." (PMID 41279139, 2025). "In another Phase II trial involving 32 patients with BRCA1/2 mutations and platinum-sensitive ovarian cancer, the combination therapy achieved a 12-week DCR of 81% and an ORR of 63%." (PMID 40395324, 2025). "In this study, we demonstrated that human TLKs play a critical role in NHEJ-mediated DSB repair and enhance PARPi sensitivity in breast and ovarian cancer cells with BRCA1 deficiency." (PMID 39844055, 2025). "has been defined as Community Type O. This is more prevalent among ovarian cancer patients and individuals with BRCA1 mutations." (PMID 41148804, 2025). "It is well established that RR-BSO reduces overall mortality in women with a pathogenic variation in BRCA1/2, plausibly due to reduced number of ovarian cancers." (PMID 40974500, 2025). "Germline mutations in BRCA1 account for a substantial proportion of hereditary breast and ovarian cancers." (PMID 41208884, 2025). "Two ovarian cancer susceptibility genes have been located: BRCA1 and BRCA2, whose mutations are inherited in an autosomal dominant manner." (PMID 40429755, 2025). "Combining CNV and BRCA1/2 mutation detection, we found that 55.0% of ovarian cancer samples were HRD+, a positive rate similar to prior studies." (PMID 41360693, 2025). "In line with this, women carrying BRCA1 mutations have a higher risk of developing breast and ovarian cancers." (PMID 40429877, 2025). "This study investigated how the location of BRCA1/2 mutations affects the benefit of PARP inhibitor maintenance therapy in newly diagnosed advanced ovarian cancer." (PMID 40075604, 2025). "Carriers of germline BRCA1/BRCA2 pathogenic variants (BRCA PVs) have increased risk of ovarian cancer (OC)." (PMID 40116830, 2025). "Background/Objectives: The breast cancer susceptibility gene 1 (BRCA1) is a tumor suppressor gene whose mutations are associated with increased susceptibility to develop breast or ovarian cancer." (PMID 40863152, 2025). "Ovarian cancers show the highest prevalence of BRCA1/2 mutations at 21% but ~5% in several other cancers, such as breast, prostate, non-small cell lung, pancreatic, bile duct, and bladder." (PMID 40274769, 2025). "This study aimed to establish a population-based cancer mutation gene registry in Colombia, focusing primarily on BRCA1/2 variants and other genes associated with breast and ovarian cancer." (PMID 40710012, 2025). "WES data of the TCGA pan-cancer cohort and an in-house ovarian cancer cohort were annotated by alterations in BRCA1/2 and additional genes causative of HRD." (PMID 40730886, 2025). "In a case-control study of ovarian cancer, patients with BRCA1 or BRCA2 mutations showed higher response rates to platinum-based chemotherapy compared to patients without such mutations." (PMID 40557004, 2025). "The small group of patients who were diagnosed with both breast and ovarian cancer had germline P/LP variants in BRCA1 (25%), BRCA2 (50%), and POLD1 (25%)." (PMID 40710012, 2025). "Patients diagnosed with a BRCA1 mutation are estimated to have a lifetime risk of ovarian cancer equal to 40–60% by the age of 80." (PMID 40869932, 2025).
ovarian carcinoma (continued). "The translational implications of R-loop research are profound, influencing our understanding of disease mechanisms, particularly in cancers with defective DNA repair mechanisms like BRCA1-deficient breast and ovarian cancers." (PMID 40271193, 2025). "Other phase Ib/II clinical trials are evaluating the efficacy of olaparib in combination with capivasertive (AKT inhibitor) or vistusertib (mTORC1/2 inhibitor) in BRCA1/2-mutated recurrent endometrial and ovarian cancer (NCT02208375)." (PMID 40274769, 2025). "The most well‐known genetic factors of hereditary breast and ovarian cancers are the high penetrance pathogenic variants in the BRCA1 (HGNC:1100) and BRCA2 (HGNC:1101) genes." (PMID 39907309, 2025). "The pathogenesis of ovarian cancer is complex, involving genetic factors such as BRCA1/2 gene mutations, as well as the synergistic effects of hormones and environmental factors, which promote the proliferation of cancer cells." (PMID 41219748, 2025). "In BRCA1-mutated ovarian cancers, the main functions identified were related to the immune system, such as MHC assembly, CD4 and CD25 regulation, and regulation of the interferon gamma pathway, among others." (PMID 40647506, 2025). "The proper function of BRCA1-BARD1 is particularly critical in cancers associated with BRCA1 mutations, such as breast and ovarian cancers." (PMID 39996778, 2025). "For instance, mutations in the BRCA1 and BRCA2 genes are strongly associated with an increased risk of breast and ovarian cancers, and genetic testing for BRCA1 and BRCA2 mutations help identify individuals at high risk." (PMID 40831536, 2025). "BABAM1 has previously been implicated as a low-penetrance risk locus that interacts with BRCA1 in both triple-negative breast cancer and ovarian cancer risk." (PMID 40775447, 2025). "This dual approach makes PARP inhibitors and immune checkpoint inhibitors a promising combination for treating BRCA1-deficient ovarian cancer." (PMID 39949780, 2025). "The increased use of genetic testing in breast and ovarian cancer patients has led to the identification of more relatives who are carriers of BRCA1/2 pathogenic variants in need of genetic counseling and preventive strategies." (PMID 40974500, 2025). "The promoter hypermethylation of the BRCA1 gene results in a loss of expression of BRCA1 in ovarian cancer." (PMID 40075848, 2025). "While the association of BRCA1 mutations with breast and ovarian cancer risks is thoroughly studied, the occurrence of other cancers that are linked to BRCA1 mutations are limited." (PMID 40406258, 2025). "Another early-onset CRC patient exhibited mosaic BRCA1 promoter methylation, typically associated with increased breast and ovarian cancer risk." (PMID 41194282, 2025). "Loss of expression of the tumor suppressor gene breast cancer susceptibility gene 1 (BRCA1) by mutation, methylation, or other mechanisms is at the origin of an increased risk of developing breast or ovary cancer." (PMID 40863152, 2025). "Studies have indicated that females with mutations in the BRCA1 gene face a 3 to 4 times higher risk of developing ovarian cancer compared to those with mutations in the BRCA2 gene." (PMID 38461424, 2024). "As tumor models, an ovarian cancer cell line with a proficient BRCA1 gene (OVCAR3) and a cell line with a mutation in the BRCA1 gene (UWB1.289) were used." (PMID 39669575, 2024). "Niraparib has demonstrated hierarchical efficacy in patients with ovarian cancer that was dependent upon the BRCA1/2 mutational and HRD statuses of their tumors." (PMID 38807759, 2024). "In many cancer types including BRCA1/2-mutated breast and ovarian cancer HR is impeded, causing high mutation burden and specific genomic imprints." (PMID 38263342, 2024).